THY1 (Thy-1 cell surface antigen)
Diseases named in the same sentence as THY1 in open-access papers (continued):
Sharing a sentence is not in itself a finding about the gene and the disease.
liver fibrosis (9 papers, 2016 to 2026). "Furthermore, Thy-1-deficient mice showed increased liver fibrosis and an upregulation of the expression of profibrogenic genes such as collagen, alpha smooth muscle cell actin (aSMA), mesothelin, and TGF-receptor I." (PMID 36768219, 2023). "In two independent studies of Collagen-α1(I)-green fluorescent protein (Col1a1GFP) mice with induced liver fibrosis, Fibulin 2, Thy-1 and elastin were overexpressed in cells considered as activated portal fibroblasts." (PMID 27065888, 2016). "Molecular docking and molecular dynamics were used to identify the most suitable therapeutic drugs and suggested that breviscapine may target THY1, which may have a therapeutic effect on liver fibrosis." (PMID 41998832, 2026). "In the future, we will continue to verify Thy1+NK’s role against liver fibrosis in animals." (PMID 40244063, 2025). "We screened the Thy1+NK subset, which exhibited a powerful killing function and could provide a new treatment approach against liver fibrosis induced by S. japonicum infection." (PMID 40244063, 2025). "The Thy1+NK cells could be used as target cells against hepatic fibrosis." (PMID 40244063, 2025). "THY1 was recently found to interact with TGFβRI, indicating a novel mechanism whereby THY1 affects TGF-β1 signalling and myofibroblast differentiation in the contest of liver fibrosis." (PMID 37501723, 2023). "When the composition of myofibroblasts was analyzed in livers of patients with liver fibrosis, the expression of MSLN and THY-1 was upregulated in livers of PSC patients, patients with biliary atresia, and biliary cirrhosis (but not in livers of patients with HCV liver fibrosis)." (PMID 34966784, 2021). "In the context of liver fibrosis Thy-1 was recently found to interact with TGFβRI, indicating a novel mechanism whereby Thy-1 affects TGF-β1 signaling and myofibroblast differentiation." (PMID 30859102, 2019). "However, the limitation is that we do not explore Thy1+NK’s role in liver fibrosis in vivo." (PMID 40244063, 2025).
periodontitis (9 papers, 2019 to 2026). An acute or chronic inflammatory process that affects the tissues that surround and support the teeth. "Thy-1/CD90 is increased in inflammatory diseases such as periodontitis and in this case, MSCs with elevated levels of Thy-1/CD90 contribute to the immunosuppressive environment that controls the inflammation." (PMID 31428610, 2019).
Alzheimer disease (8 papers, 2014 to 2025). A progressive, neurodegenerative disease characterized by loss of function and death of nerve cells in several areas of the brain leading to loss of cognitive function such as memory and language. "These alterations recapitulate many of the early cerebral vascular changes seen in AD patients, which are not seen in the 5x familial Alzheimer’s disease (FAD) transgenic mouse model, in which the overexpression of APP is targeted to neurons by the Thy1 promoter." (PMID 40141075, 2025).
diabetes (8 papers, 2013 to 2025). "We did not observe diabetes-associated changes in gene expression of cellular identity genes, such as Itga5, Ly6a (SCA1), and Thy1; however, diabetes was associated with changes in gene expression of ECM- and inflammation-related genes." (PMID 34944568, 2021). "Diabetes diminished the number of Thy-1-CFP fluorescent cells by 16%, confirming earlier quantification studies." (PMID 41002420, 2025). "A mouse model of streptozotocin induced diabetes was used that expresses yellow fluorescent protein (YFP) in peripheral nerve fibers under the thy-1 promoter." (PMID 35589940, 2022).
lymphoma (8 papers, 2010 to 2024). A malignant (clonal) proliferation of B- lymphocytes or T- lymphocytes which involves the lymph nodes, bone marrow and/or extranodal sites. "In order to evaluate fOSGN2-P generation in lymphoblastoid cells incapable of generating mature DLO, the DPM synthase deficient (null mutation in mouse DPM1 gene) mouse lymphoma cell line Thy-1 along with its parental cell line (BW5147.3) were examined." (PMID 20652024, 2010). "Similarly, co-culture experiments using neuronal cells expressing Thy-1 on their surface can also stimulate cytoskeletal changes that lead to astrocyte migration, which were also observed after stimulating astrocytes with EL4 cells, a lymphoma-derived cell line that expresses high levels of Thy-1." (PMID 38099295, 2023). "In anti-thymocyte/Thy-1 autoreactive μκ transgenic (ATAμκ Tg) Pla2g2a+ BALB/c background C.B17 mice generated NKT2 cells that continuously control CD1d+ B1 B cells through old aging and lost CD1d in B1 B cells generating strong B1 ATA B cell leukemia/lymphoma." (PMID 36050343, 2022). "CD45.2+ lymphoma cells were negative for all evaluated B‐cell markers, including CD19, CD20, and Pax5, and instead expressed T‐cell markers CD3, Thy1, and TCRβ." (PMID 35510955, 2022).
pancreatic ductal adenocarcinoma (8 papers, 2016 to 2025). An infiltrating adenocarcinoma that arises from the epithelial cells of the pancreas. "In this work, we analyze the expression levels and prognostic value of stromal tumor-infiltrating lymphocyte (CD4, CD8, and CD20) and cancer-associated fibroblast (Thy-1, FAP, and SMA) subpopulations in a cohort of pancreatic ductal adenocarcinoma patients." (PMID 34771664, 2021). "In vivo molecular imaging using Thy1-scFv (single-chain variable fragment) conjugated to an ultrasound contrast agent (MBThy1-scFv) demonstrated signal enhancement on a transgenic pancreatic ductal adenocarcinoma (PDAC) mouse model, suggesting potential for the early diagnosis of PDAC." (PMID 38137745, 2023).
endometriosis (7 papers, 2017 to 2025). The growth of functional endometrial tissue in anatomic sites outside the uterine body. "This led us to investigate two soluble molecules, CD83 and CD90/Thy-1, which have not yet been tested in connection with endometriosis." (PMID 35769819, 2022).
glomerulosclerosis (7 papers, 2011 to 2023). A hardening of the kidney glomerulus caused by scarring of the blood vessels. "Chronic anti-thy1-induced glomerulosclerosis was accompanied by prominent renal macrophage infiltration and cell proliferation, both in the tubulointerstitial and glomerular compartment." (PMID 24119229, 2013). "Therapy with Imatinib limits the progressive course of chronic anti-thy1 glomerulosclerosis towards tubulointerstitial fibrosis and renal insufficiency." (PMID 24119229, 2013). "Taken together, the present study demonstrates that inhibition of tyrosine kinases signal transduction limits the progressive course of anti-thy1-induced chronic renal disease towards glomerulosclerosis, tubulointerstitial fibrosis and renal insufficiency." (PMID 24119229, 2013). "In contrast, rats with progressive anti-thy1-induced glomerulosclerosis expressed marked increases in glomerular and tubulointerstitial α-SMA expression (1.25 ± 0.53% and 1.96 ± 0.93%, p < 0.001 vs. 1-K Controls)." (PMID 24119229, 2013). "In a model of chronic anti-thy1-induced mesangioproliferative glomerulosclerosis, we found that administration of Imatinib slows its progressive course toward chronic renal fibrosis and insufficiency." (PMID 24119229, 2013). "Compared to controls, the induction of chronic progressive anti-thy1 induced glomerulosclerosis increased mRNA expression of PDGF-A, B, C and D as well as PDFG receptor-α and receptor-β." (PMID 24119229, 2013). "Anti-thy1 glomerulosclerosis was induced by injection of anti-thy1 antibody into uninephrectomized Wistar rats." (PMID 24119229, 2013). "In this respect, low-dose rapamycin (2.5 mg/kg−1/body weight−1 in rats) confers antiproteinuric effects in a chronic model of progressive mesangioproliferative nephropathy, that is, anti-thy1-induced glomerulosclerosis in the rat." (PMID 22685654, 2012). "Briefly, rapamycin remarkably limits the progressive course of chronic anti-thy1 antibody-induced renal disease towards glomerulosclerosis, tubulointerstitial fibrosis, and renal insufficiency." (PMID 22685654, 2012). "Next, to examine the effect of PP2 on the morphological changes seen in Thy1 GN glomerulosclerosis, we examined Col4 and SMA expression in the two groups." (PMID 21445358, 2011). "Untreated Thy1 GN rats showed an increased degree of glomerulosclerosis, whereas glomerulosclerosis was significantly decreased in the PP2-treated group, along with renal function." (PMID 21445358, 2011). "Animals with chronic anti-thy1 glomerulosclerosis showed significant increases in blood creatinine (2.43 ± 2.12 mg/dL) and urea concentrations (232 ± 182 mg/dL) and decrease in creatinine clearances (0.24 ± 0.16 mL/min) (all P < 0.01 vs. 1-K Control), indicating chronic renal insufficiency." (PMID 24119229, 2013). "However, the outcome of mTOR inhibition in anti-thy1-induced glomerulosclerosis contrasts with the one previously reported in anti-thy1-induced acute glomerulonephritis." (PMID 22685654, 2012). "Therefore, this study in chronic anti-thy1 mesangioproliferative glomerulosclerosis proved that the inhibition of tyrosine kinases signalling through Imatinib directly or indirectly interferes with multiple key pathways to slow the progression of chronic renal disease." (PMID 24119229, 2013).
Stroke (7 papers, 2018 to 2025). Sudden impairment of blood flow to a part of the brain due to occlusion or rupture of an artery to the brain. "A closer examination of sparsely labeled axons in the Thy1-YFP mouse shows both a complete loss of axons with the stroke core as well as the formation of retraction bulbs within the peri-infarct, a clear hallmark of axon degeneration." (PMID 37821228, 2023). "In contrast, MEC17 overexpression significantly rescued the injury to dendritic spines after stroke compared with the MCAO + Thy1 CreERT2‐eYFP group (p < 0.05)." (PMID 36965035, 2023). "Conversely, MEC17 overexpression in the pyramidal neurons significantly alleviated the motor dysfunction after stroke compared with the MCAO + Thy1 CreERT2‐eYFP group." (PMID 36965035, 2023). "MEC17 knockout in the pyramidal neurons aggravated the behavioral dysfunction compared with the MCAO + Thy1 CreERT2‐eYFP group from Day 1 to 4 weeks after stroke." (PMID 36965035, 2023). "To determine imaging signatures of focal cellular changes after acute stroke (24 h post-stroke), we first compared group-level heat-maps for Thy1-expressing neuron (YFP) counts and cell nuclei (PI) with MRI measures." (PMID 31796741, 2019). "PI was chosen to complement the relatively sparse Thy1-YFP labeling for defining the stroke core since it is a more sensitive nuclear label." (PMID 31796741, 2019). "On the microscopic level, we detected the most prominent loss of Thy1-YFP neurons in layer 5 of the somatosensory cortex, a region delineated on T2-weighted images as part of the stroke lesion." (PMID 31796741, 2019). "Interestingly, MEC17 knockout in the pyramidal cells did not affect the density of mushroom‐shaped mature dendritic spines (p > 0.05) but aggravated the injury to dendritic spines after stroke compared with the MCAO + Thy1 CreERT2‐eYFP group (p < 0.01)." (PMID 36965035, 2023). "Even though the Thy-1 promoter lacks hypoxia regulatory elements, Thy-1 expression can be enhanced by Hif-1 downstream targets, such as cytokines and growth factors, as observed in the hypoxic-ischemic brain after injury or stroke." (PMID 35186924, 2022). "Through analysis of hemisphere asymmetry in Thy1-YFP labeling (image intensity) across these tracts, we found cellular and fiber density changes in the VTA tracts but not the control RSP tracts (when comparing stroke and control mice)." (PMID 31796741, 2019).
tauopathy (7 papers, 2019 to 2025). Neurodegenerative disorders involving deposition of abnormal tau protein isoforms (tau proteins) in neurons and glial cells in the brain. "To study the in vivo effect of tetrandrine on tau-associated pathology, we employed Thy1-hTau.P301S mice as a tauopathy model." (PMID 36273169, 2022). "Six-month-old PS19 tauopathy mice carrying the Thy1-YFP reporter have been used to demonstrate tauopathy-related axonal spheroids." (PMID 38049707, 2024). "Next, we analyzed BTK levels in the Thy1-hTau.P301S tauopathy mouse model." (PMID 30758770, 2019).
Cirrhosis (6 papers, 2013 to 2025). A chronic disorder of the liver in which liver tissue becomes scarred and is partially replaced by regenerative nodules and fibrotic tissue resulting in loss of liver function. "In contrast, in cirrhosis, THY1+ and THY1−ACTA2high were both present, without a distinct CXCL8+ subset." (PMID 35320046, 2022).
esophageal cancer (6 papers, 2014 to 2024). A primary or metastatic malignant neoplasm involving the esophagus. "Meanwhile, over-expression of THY1 also predicted poor (DFS) in esophageal carcinoma, kidney renal papillary cell carcinoma, prostate adenocarcinoma, skin cutaneous melanoma, and uveal melanoma." (PMID 38819947, 2024).
gastric tumors (6 papers, 2014 to 2025). "This dual role as both a marker of and a potential participant in the EMT may offer a biological explanation for the association between high THY1 expression and a poor prognosis for patients with gastric tumors." (PMID 40476057, 2025). "Notably, our group has also shown in prior work that the EMT and matrix remodeling are hallmark processes characterizing gastric tumors with high THY1 expression." (PMID 40476057, 2025).
HCMV infection (6 papers, 2015 to 2023). "HCMV infects multiple cell types including stem cells; referring to the fact that Thy-1 and platelet-derived growth factor receptor alpha (PDGFRα) stem cell markers enhance HCMV infection, stem cells are susceptible to HCMV infection." (PMID 34566995, 2021). "We identified THY-1, a protein on the surface of many different cell types susceptible to CMV infection, as having an important role for facilitating virus infection." (PMID 26147640, 2015). "THY-1 is expressed in many cell types both in vivo and in vitro, including epithelial and endothelial cells, smooth muscle cells, placenta, neurons, hepatocytes, and hematopoietic stem cells, the same cells that are susceptible to HCMV infection." (PMID 26147640, 2015). "To determine whether THY-1 is important for HCMV infection, we performed a series of loss-of-function experiments." (PMID 26147640, 2015). "Expression of exogenous THY-1 increased susceptibility of cells to HCMV infection." (PMID 26147640, 2015). "CD147 and CD151 (tetraspanin) and THY-1 (CD90) have also been found to play a role during HCMV infection of some cell types." (PMID 34025614, 2021). "THY-1 cell surface antigen (CD90) is reported to play a role in the early stage of HCMV infection, probably by facilitating viral entry via a macropinocytosis-like process." (PMID 31356650, 2019). "Using a computational biology approach, correlating gene expression with virus infectivity in 54 cell lines, we identified THY-1 as a putative host determinant for HCMV infection in these cells." (PMID 26147640, 2015). "Since the infection was restricted to the initial 60 min of viral inoculation, we conclude that exogenous expression of THY-1 enhances the initial stage of HCMV infection of cells." (PMID 26147640, 2015). "To confirm the loss-of-function findings observed with THY-1 specific antibody, we used THY-1 specific siRNAs to knockdown THY-1 expression in permissive cells, and analyzed the effect on HCMV infection." (PMID 26147640, 2015). "Previous studies have shown that THY-1 is down-regulated in fibroblasts, as well as in mesenchymal stem cells upon HCMV infection in a manner similar to that of PDGFR-α." (PMID 26147640, 2015). "Here, we report that THY-1 has an important role in the early stages of HCMV infection in a diverse group of cell lines." (PMID 26147640, 2015). "We found that antibody to THY-1 or soluble THY-1 protein blocked HCMV infection in multiple cell types, suggesting that THY-1 might serve as a potential therapeutic target to reduce infection." (PMID 26147640, 2015). "In contrast with SNB-19 and HS-578T cells which support HCMV infection and express THY-1 on their surface (used above in loss-of-function experiments), SF-539 (gliosarcoma) cells express negligible levels of THY-1 mRNA or THY-1 protein on the cell surface, and are refractory to HCMV Towne infection." (PMID 26147640, 2015). "THY-1 antibody also blocked HCMV infection in primary MRC-5 cells." (PMID 26147640, 2015). "We postulated that since THY-1 is important for HCMV infection, it might interact with one or more of these glycoproteins, either directly or as part of a complex." (PMID 26147640, 2015). "Thus, we have identified THY-1 as a molecule that has an important role in the initial stage of HCMV infection." (PMID 26147640, 2015). "Therefore, THY-1 may be part of a multimolecular complex mportant for the initial phase of CMV infection and signaling (that includes PDGFR- α, EGFR, integrins, paxillin, and viral glycoproteins)." (PMID 26147640, 2015). "However, there are differences between subpopulations of progenitor cells: CD34+/CD38− cells support an HCMV infection with the hallmarks of latency, but a subset of CD34+/CD38− cells expressing a stem cell phenotype (lineage−/Thy-1+) support productive HCMV infection." (PMID 32296651, 2020). "Soluble THY-1 protein blocked HCMV infection during, but not after, virus internalization." (PMID 26147640, 2015).
HCMV infection (continued). "Since THY-1 interacts with several other cellular proteins, including integrins and is important in multiple signaling pathways, it is likely that THY-1 facilitates HCMV infection at an early stage as an entry mediator, rather than a receptor for a viral glycoprotein(s)." (PMID 26147640, 2015).
ischemia (6 papers, 2007 to 2016). A hypoperfusion of the BLOOD through an organ or tissue caused by a PATHOLOGIC CONSTRICTION or obstruction of its BLOOD VESSELS, or an absence of BLOOD CIRCULATION. "Simulated ischemia, however, caused an almost 50% reduction in the number of NeuN-labelled cells compared with controls (n = 9; p = 0.021) and a similar decrease in THY-1 mRNA levels (n = 8; p = 0.010), indicating a reduction in RGC number." (PMID 25635827, 2015). "The eyes stored at 21°C showed after 100 and 340 min of ischemia significantly higher Thy-1 mRNA levels than the eyes stored at 37°C in the two-sided t-test (p<0.05)." (PMID 26848953, 2016). "Thy-1 is primarily expressed by RGCs within the retina, some RGC stressors, including increased IOP, optic nerve crush, ischemia and intravitreal injection of excitatory amino acid have been shown to decrease the levels of thy-1 mRNA and protein in RGCs." (PMID 22457807, 2012). "In contrast to eyes kept at 37°C the eyes stored at 21°C still showed spontaneous ganglion cell spiking (56.8% versus 0%), a 5.8 fold higher Thy-1 mRNA expression (not significant, but a trend) and a preserved retinal structure after 340 minutes of ischemia." (PMID 26848953, 2016).